DPP4 (dipeptidyl peptidase 4)
Diseases named in the same sentence as DPP4 in open-access papers (continued):
Sharing a sentence is not in itself a finding about the gene and the disease.
type 2 diabetes (continued). "Nevertheless, some type 2 diabetes medications such as the dipeptidyl peptidase-4 inhibitors have reported to lead to a hot swollen joint with severe pain that mimics SA." (PMID 35366159, 2022). "Sitagliptin (SIT), an inhibitor of dipeptidyl peptidase-4 (DPP-4) mainly used for type II diabetes mellitus, was reported to antagonize IR injury in the liver, kidney, intestine, and testis." (PMID 36474576, 2022). "Sodium-glucose co-transporter-2 (SGLT2) inhibitors and dipeptidyl peptidase-4 (DPP4) inhibitors are increasingly used as second-line therapies in patients with type 2 diabetes." (PMID 35673518, 2022). "Recently, a new group of drugs has been added to the treatment of type II diabetes mellitus, known as dipeptidyl peptidase-4 inhibitors (DPP4-is)." (PMID 35126393, 2022). "In the following two decades, various small molecule DPP4 inhibitor substances have been developed and tested in subsequent clinical studies for the therapy of type 2 diabetes and for other cardiovascular comorbidities." (PMID 35884882, 2022). "When managing type 2 diabetes, the family of oral antidiabetic medicines known as dipeptidyl peptidase-4 (DPP-IV) inhibitors is well-established." (PMID 36615348, 2022). "Vildagliptin (VG) is an orally administered selective inhibitor of dipeptidyl peptidase 4 (DPP4) indicated for the treatment of type-2 diabetes." (PMID 34959439, 2021). "Gemigliptin is a potent DPP-4 inhibitor that has been approved for use among patients with type 2 diabetes and provides pleiotropic effects in addition to its glucose-lowering effects." (PMID 34697593, 2021). "In view of these significant results, compound 5d, which combines both α-glucosidase and DPP-4 inhibitory activities, presents great potential as a lead compound for the development of a novel dual inhibitor treatment strategy for type 2 diabetes." (PMID 33672038, 2021). "Seventy-six patients (67.3%) suffered from type 2 Diabetes and 52 (46%) were treated with dipeptidyl-peptidase 4 inhibitors." (PMID 33573656, 2021). "Dipeptidyl peptidase-4 (DPP-4) inhibitors used to treat type 2 diabetes are considered a new oral medication of antidiabetic therapy." (PMID 34976524, 2021). "The present study revealed that DPP‐4 inhibition reduces left ventricular stiffening in a rat model of combined type 2 diabetes, hypertension, and obesity, in part by modulating titin cleavage, isoform switching, and phosphorylation." (PMID 33295687, 2021). "DPP-4 inhibitors (DPP-4i) represent a class of oral antihyperglycemic agents used for the treatment of Type 2 diabetes (T2D), which have also been reported to play anti-inflammatory and immunomodulatory properties." (PMID 33906375, 2021). "DPP4 inhibitors, such as sitagliptin, linagliptin, vildagliptin, and saxagliptin, have good efficacy, safety and tolerability in the treatment of type II diabetes." (PMID 34926239, 2021). "Linagliptin is a DPP-4 inhibitor approved by the Food and Drug Administration in 2011 as a treatment for type 2 diabetes and is as effective as other DPP-4 inhibitors." (PMID 35002970, 2021). "Accordingly, GLP-RAs and DPP-4 inhibitors are a well-established class of glucose-lowering agents for treating type 2 diabetes." (PMID 34205659, 2021). "Teneligliptin (TEN) is a dipeptidyl peptidase-4 inhibitor (DPP-4i) approved to treat type 2 diabetes." (PMID 34573072, 2021). "Omarigliptin is a novel once-weekly dipeptidyl peptidase-4 (DPP-4) inhibitor developed for the treatment of type 2 diabetes." (PMID 34804998, 2021). "We investigated the drug repurposing potential of a library of dipeptidyl peptidase 4 (DPP4) inhibitors which are currently marketed for type-2 diabetes as treatment option for SARS-CoV-2 infections." (PMID 33430081, 2021). "Diastolic dysfunction and left ventricular stiffening are positively associated with elevated circulating dipeptidyl peptidase‐4 (DPP‐4) levels in type 2 diabetes and obese patients." (PMID 33295687, 2021).
type 2 diabetes (continued). "DPP4 plays an important role in the pathogenesis of type 2 diabetes, obesity and cardiovascular diseases." (PMID 34926239, 2021). "Its importance has been highlighted by the approval of DPP4 inhibitors as an established glucose-lowering therapy in type 2 diabetes." (PMID 33796097, 2021). "Sitagliptin (SN), an orally active, potent dipeptidyl-peptidase inhibitor [DPP-4 inhibitor has recently been approved (listed in top 20 drugs in 2017) for the therapy of type 2 diabetes." (PMID 33345632, 2021). "Subsequent clinical studies during the 2000s showed a glucose-lowering authority of DPP4 inhibitors in humans with type 2 diabetes as monotherapy or in combination with other therapies, i.e., metformin, sulfonylureas, tiazolidinediones, or exogenous insulin." (PMID 33796097, 2021). "Dipeptidyl peptidase 4 (DPP-4) is selected as an example because of its essential role in the discovery of drugs for type 2 diabetes and several types of cancer." (PMID 33976191, 2021). "Because of its enzymatic action, such as the degradation of incretin hormones, DPP-4/CD26 is recognized as the significant therapeutic target for type 2 diabetes (T2DM); DPP-4 inhibitors have been used as an anti-diabetic agent for a decade." (PMID 34063285, 2021). "Dipeptidyl peptidase-4 (DPP-4) inhibitors are widely used incretin-based therapy for the treatment of type 2 diabetes." (PMID 33073318, 2021). "Patients aged ≥ 18 years with type 2 diabetes initiating empagliflozin or a dipeptidyl peptidase‐4 (DPP‐4) inhibitor were 1:1 propensity score (PS) matched into sequentially built cohorts of new users naïve to both drug classes." (PMID 33532619, 2021). "Since the introduction of DPP4-is as a standard treatment regimen for type 2 diabetes, numerous cases of patients developing BP following this treatment have been published." (PMID 33573656, 2021). "It has been reported that the addition of a DPP-4 inhibitor to patients with type 2 diabetes that is inadequately controlled by an α-glucosidase inhibitor achieved better glycemic control without further increasing the risk of weight gain and hypoglycemia." (PMID 33672038, 2021). "An ethanol extract of HRS significantly inhibited DPP-4 activity, increased insulin release, and thus, improved glucose tolerance in type 2 diabetic rats." (PMID 34203048, 2021). "DPP-4 inhibitors are recommended for use as second- or third-line treatment for type 2 diabetes in several international guidelines and in Australian guidelines." (PMID 34256874, 2021). "In animal models and clinical studies of type 2 diabetes, dipeptidyl peptidase-4 inhibitors appear to have many cardiometabolic, anti-inflammatory, and immunoregulatory benefits in addition to their glucoregulatory actions." (PMID 33679779, 2021). "DPP-4 inhibitors are known to be effective in the treatment of type 2 diabetes by regulating insulin and glucagon secretion with few major side effects." (PMID 34205264, 2021). "Accordingly, several DPP4 inhibitors such as sitagliptin are approved for the management of type 2 diabetes, as DPP4 inhibition in this context prolongs the half-life of GLP1 and GIP, increasing endogenous insulin secretion." (PMID 33513866, 2021). "Accumulating evidence has now suggested that the beneficial effects of DPP-4 inhibitors include not only type 2 diabetes, but also specific cardiovascular diseases." (PMID 33401457, 2021). "Sitagliptin is a dipeptidyl peptidase-4 (DPP-4) inhibitor used to treat type 2 diabetes and commercialized by Merck and Co. under the name Januvia." (PMID 33498521, 2021). "Thereafter, the nanoparticle was applied to edit dipeptidyl peptidase-4 gene (DPP-4) in liver tissues for type 2 diabetes treatment." (PMID 34683943, 2021). "Sitagliptin (Sit), a dipeptidyl peptidase-4 (DPP-4) inhibitor, is commonly prescribed for the treatment of adult-onset diabetes." (PMID 34475715, 2021).
type 2 diabetes (continued). "A meta-analysis revealed that dipeptidyl peptidase IV inhibitor (DPP-4) inhibitors were significantly more effective than other oral antihyperglycemic drugs at reducing GV in patients with type 2 diabetes." (PMID 34575189, 2021). "Inspired by this study, we started scanning the chemical structures of known FDA approved drugs for repurposing and were intrigued by dipeptidyl peptidase IV (DPP4 or CD26) inhibitors which are used in the treatment of type-2 diabetes." (PMID 33430081, 2021). "The activity of DPP4 seems to be increased in patients with type 2 diabetes, and various in vitro and in vivo studies have demonstrated that this enzyme can interact with proinflammatory pathways." (PMID 33691757, 2021). "First, we examined the nationwide registered data and studied the incidence of PD transition to HD (i.e., defined as PD failure) among ESRD patients who had regularly received different kinds of DPP4 inhibitor for controlling type 2 diabetes." (PMID 33514826, 2021). "Many patients with type 2 diabetes are taking dipeptidyl peptidase 4 inhibitors (DPP-4is) or glucagon-like peptide-1 receptor agonists (GLP1-RAs)—both of which work through the incretin pathway in the gut." (PMID 34083744, 2021). "In our study, we demonstrated that both empagliflozin, a SGLT2 inhibitor, and linagliptin, a DPP4 inhibitor, attenuate diabetic kidney disease by promoting glomerular autophagy in db/db mice, a model of type 2 diabetes." (PMID 32340263, 2020). "In the whole sample 7 (4.68%) patients were taking dipeptidyl peptidase-4 (DPP4) antagonists as treatment for type 2 diabetes." (PMID 33192409, 2020). "Alogliptin is a selective inhibitor of dipeptidyl peptidase 4 (DPP-4) approved for the treatment of type 2 diabetes." (PMID 32493335, 2020). "We aimed to assess the effect of the SGLT2 inhibitor empagliflozin, the DPP4 inhibitor linagliptin, and their combination, on glomerular autophagy in a model of type 2 diabetes." (PMID 32340263, 2020). "To date, no published data are available to directly compare glycemic and pleiotropic effects in real-world type 2 diabetes patients initiating SGLT2 inhibitors or DPP4 inhibitors." (PMID 32050968, 2020). "Evogliptin (Evo), a novel DPP-4 inhibitor, was recently approved for type 2 diabetes by the South Korean Ministry of Food and Drug Safety." (PMID 32937958, 2020). "Natural molecules like Myr, a potent DPP-4 inhibitor, can be of great value and a potential adjunct therapeutic molecule for managing type 2 diabetes." (PMID 32282828, 2020). "The EXAMINE trial tested the efficacy and safety of alogliptin, an inhibitor of dipeptidyl peptidase 4, compared with placebo in 5380 patients with type 2 diabetes and a recent acute coronary syndrome." (PMID 32493335, 2020). "The protease dipeptidyl peptidase 4 (DPP4) is a pharmacological target in type 2 diabetes therapy primarily because it inactivates glucagon-like protein-1." (PMID 33218025, 2020). "We included patients newly receiving SGLT2 inhibitor or DPP4 inhibitor intensification therapy for type 2 diabetes from 2016 to 2017." (PMID 32050968, 2020). "Dipeptidyl peptidase-4 (DPP-4) inhibitors are commonly used to lower glucose in Type 2 diabetes, although within the class they are quite diverse in their chemical structures." (PMID 32796688, 2020). "We assessed the relationship between baseline characteristics and genital infection in 21 004 people with type 2 diabetes initiating SGLT2i and 55 471 controls initiating dipeptidyl peptidase-4 inhibitors (DPP4i) in a UK primary care database." (PMID 32448787, 2020). "Retagliptin phosphate: Retagliptin phosphate is under investigation as a DPP-4 inhibitor for treating type-2 diabetes." (PMID 32509033, 2020). "In comparison to conventional ELISA, receptor-mediated bioassay reflects dynamic change of GIP by DPP-4 inhibitor treatment in subjects with type 2 diabetes." (PMID 32390941, 2020).
type 2 diabetes (continued). "In the current decade, DPP-4 inhibitors are often used to treat the common form of type 2 diabetes in Japan." (PMID 33373317, 2020). "In a prospective study from Italy, variations in DPP4 activity over 3 months in type 2 diabetic patients showed a significant positive correlation with variations in HbA1c." (PMID 33312197, 2020). "Dipeptidyl peptidase-4 (DPP-4) inhibitors, including linagliptin, sitagliptin, and vildagliptin (V), are class of hypoglycemic agents used for treating type II diabetes through inhibition of glucagon-like peptide-1 (GLP-1) degradation." (PMID 32102588, 2020). "The rationale for using a DPP-4 inhibitor in our studies was based on its lipid lowering and anti-oxidative properties, and also because many type 2 diabetics have lipid abnormalities like hypercholesterolemia and take this drug to manage their blood glucose." (PMID 31921324, 2020). "Dipeptidyl peptidase-4 (DPP-4) inhibitors are a class of drugs approved for the treatment of type 2 diabetes." (PMID 32032367, 2020). "The gliptin family of drugs that inhibit DPP4 has attracted interest in treating patients with type 2 diabetes." (PMID 32104696, 2020). "Modulation of the incretin signalling system by either GLP-1 analogues directly or by stabilising the circulating GLP-1 by inhibition of dipeptidyl peptidase 4 (DPP4) is currently used as a treatment strategy for type 2 diabetes." (PMID 32894317, 2020). "Sitagliptin is used to decrease the level of blood sugar in patients with type 2 diabetes and belongs to the dipeptidyl peptidase-4 (DPP-4) class of inhibitors." (PMID 32509033, 2020). "Given our observations, the effects of SGLT2 inhibitors and DPP4 inhibitors on weight should be considered when individualizing type 2 diabetes therapy." (PMID 32050968, 2020). "A considerable proportion of our study population (34%) suffered from type 2 diabetes, a condition in which plasma DPP4 activity is altered and DPP4 inhibitors are commonly used oral antidiabetics." (PMID 33192409, 2020). "Among the various medications available for type 2 diabetes, oral glucose-lowering agents such as dipeptidyl peptidase 4 (DPP-4) inhibitors and sodium-glucose cotransporter-2 (SGLT2) inhibitors have recently become the focus of substantial research." (PMID 31910850, 2020). "The inhibition of DPP-4 with DPP-4 inhibitors is used to improve anti-hyperglycaemic therapy in type 2 diabetes." (PMID 33328991, 2020). "DPP4 expression is enhanced on blood T lymphocytes from type 2 diabetic patients and correlates with insulin resistance and glycated hemoglobin." (PMID 32848769, 2020). "DPP-4 inhibitors, gliptins, are used for the treatment of type II diabetes, with seventeen drugs of this type mentioned in the WHO drugs stem book." (PMID 32485894, 2020). "Human DPP4 (PDB ID 5J3J) was found to be associated with glucose metabolism, and various DPP4 inhibitors have been released as therapeutic drugs for type 2 diabetes." (PMID 32104696, 2020). "In the present study, we analyzed Taiwan’s multi-institutional electronic medical records to compare head-to-head the glucose-lowering effects of SGLT2 inhibitors vs. DPP4 inhibitors in type 2 diabetes patients." (PMID 32050968, 2020). "This study aimed to investigate the effects of DPP-4 inhibitors on the progression of diabetic retinopathy in patients with type 2 diabetes based on the diabetic retinopathy severity scale." (PMID 32190049, 2020). "In Malaysia, for more than a decade, dipeptidyl peptidase-4 inhibitors (DPP-4i) are among the oral antidiabetic medications used as monotherapy or in combination to manage type II diabetes mellitus (T2DM)." (PMID 32566235, 2020). "Dipeptidyl peptidase-4 (DPP4)-inhibitors, used clinically to treat type 2 diabetes, have in murine models been shown to attenuate aneurysm formation and decrease aortic wall matrix degradation, inflammation and apoptosis." (PMID 31971988, 2020).
type 2 diabetes (continued). "The efficacy and safety profile of the DPP-4 inhibitors shows a favorable profile of the DPP-4 inhibitors especially for patients with renal impairment as well as elderly subjects with type-2-diabetes." (PMID 31275246, 2019). "We, for the first time, evaluated the effects of DPP-4 inhibitors on lipid and lipoprotein profiles in patients with type-2 diabetes undergoing statin treatment." (PMID 31905896, 2019). "One is that the development of DPP-4 inhibition is a rational drug design based in scientific studies on pathophysiology of type 2 diabetes and that the development shows that it is important to target both the impaired insulin secretion and the high glucagon." (PMID 31275243, 2019). "Dipeptidyl peptidase-4 inhibitors (DPP4i) are a class of orally available, small molecule inhibitors for the treatment and management of Type-II diabetes, which have been on the market for over 10 years." (PMID 30894647, 2019). "DPP-4 inhibitors have also been examined in placebo-controlled studies in subjects with type 2 diabetes and chronic renal insufficiency, including patients with end-stage renal disease on dialysis." (PMID 31275243, 2019). "Subsequent clinical studies during the 2000s showed a glucose-lowering action of DPP-4 inhibitors also in human subjects with type 2 diabetes." (PMID 31275243, 2019). "Systemic inhibition of dipeptidyl peptidase 4 (dpp4) represents an effective and established treatment option for type 2 diabetes (T2D)." (PMID 31794591, 2019). "Linagliptin is a dipeptidyl peptidase-4 inhibitor which is clinically approved to reduce hyperglycemia in type 2 diabetes." (PMID 31139140, 2019). "DPP-4 inhibitors have become an increasingly firmly established class of oral antidiabetic agents for the treatment of type 2 diabetes." (PMID 31275246, 2019). "DPP-4 inhibitors are implemented into the treatment algorithms of type 2 diabetes in many national and international guidelines." (PMID 31275246, 2019). "Numerous patients with type 2 diabetes still have poor glycemic control after receiving several classes of OHAs or newer and more expensive agents including dipeptidyl peptidase-4 (DPP-4) inhibitors and sodium-glucose cotransporter 2 inhibitors." (PMID 31415655, 2019). "Overall, therefore, these studies assure the safety of DPP-4 inhibitors when used as glucose-lowering treatment of type 2 diabetes." (PMID 31275243, 2019). "The indications for Dipeptidyl Peptidase 4 Inhibitors in patients with type 2 diabetes and CKD have been analyzed over the last 10 years." (PMID 31212945, 2019). "Recently, dipeptidyl peptidase-4 (DPP-4) inhibitors have emerged as useful tools for treating type 2 diabetes." (PMID 31237881, 2019). "Dipeptidyl peptidase-4 inhibitors (DPP4i) are a class of orally available, small molecule inhibitors for the management of Type-II diabetes." (PMID 30894647, 2019). "These drugs include thrombin and factor Xa inhibitors (used as oral anticoagulants), dipeptidyl-peptidase 4 (DPP4) inhibitors, used for type-2 diabetes, as well as novel experimental inhibitors of mast cell chymases." (PMID 31956307, 2019). "GLP-1-analogues and DPP-4-inhibitors are well-established treatments in type 2 diabetes and recently two major studies of GLP-1-analogues have shown, in addition to lowering blood glucose, a reduced risk of cardiovascular disease and mortality." (PMID 30670722, 2019). "Beyond DPP4 enzyme role in the pathophysiology of type 2 diabetes, this protein is also an adipo-myokine and, therefore, it is supposed to be related to lean and fat masses." (PMID 30886868, 2019). "Curiously, a meta-analysis of ten randomized controlled trials evaluating the impact of DPP4 inhibitors on serum adiponectin of patients with type 2 diabetes confirmed significantly elevated adiponectin levels after the pharmacological inhibition of DPP4." (PMID 30886868, 2019).